YWHAG (tyrosine 3-monooxygenase/tryptophan 5-monooxygenase activation protein gamma)
Diseases named in the same sentence as YWHAG in open-access papers (continued):
Sharing a sentence is not in itself a finding about the gene and the disease.
cancer (continued). "We identified YWHAG as a hub gene with broad engagement across the spectrum of human cancers." (PMID 37759388, 2023). "By increasing autophagic flux, YWHAG protects cancer cells from oxidative catastrophe during EMT." (PMID 37759388, 2023). "Our earlier observations suggest that YWHAG‐enhanced autophagy may protect cancer cells undergoing EMT from catastrophic levels of oxidative stress." (PMID 37759388, 2023). "Unlike YWHAG‐deficient cancer cells, YWHAE or YWHAH deficiency did not affect EMT induced by DMOG and TGF‐β." (PMID 37759388, 2023). "When combined with our previous data, these new findings demonstrate the critical role of YWHAG in the initiation and maintenance of cancer EMT, and the knockdown of YWHAG may promote MET as well." (PMID 37759388, 2023). "The overexpression of YWHAG has been observed in various cancer types." (PMID 31240215, 2019). "The expression of YWHAG and HSP90AA1 was significantly correlated in 21 cancer types from the TCGA database." (PMID 37759388, 2023). "In this study, we showed that the regulome of the oncogenic signaling adaptor YWHAG is a key constituent of EMT and metastasis mechanisms with broad clinical impact across different human cancer types." (PMID 37759388, 2023). "To establish a role for YWHAG in EMT, we examined the effect of YWHAG suppression on either DMOG‐ or TGF‐β1‐induced EMT in cancer cells." (PMID 37759388, 2023). "This global unbiased meta‐analysis indicator strengthened the negative impact of YWHAG on the survival of patients diagnosed with different types of cancers." (PMID 37759388, 2023). "Based on the Cancer Genome Atlas (TCGA) cancer database, we used LASSO regression analysis to identify the six prognostic-related genes with both DDR and EMT functions, including TP63, YWHAZ, BRCA1, CCND2, YWHAG, and HIPK2." (PMID 36673982, 2023). "Indeed, overexpression of autophagic proteins (autophagy related protein 5 (ATG5), Beclin and light chain 3 alpha/beta (LC3A/B)) in three cancer cell lines was detected during EMT, which was diminished in YWHAG‐knockdown cells." (PMID 37759388, 2023). "Moreover, inflammatory dysregulation is an intrinsic mechanism in several cancers, and YWHAZ and YWHAG are a family of phosphoserine/threonine-binding molecules that can be indirectly degraded by Serpina3n." (PMID 36673982, 2023). "At the single nucleotide polymorphism (SNP) mutation level and transcriptional level, we found that MAP4, YWHAG, KSR2, SPAG9, and CEP250 gene-related loci are different in cancer and paracancer tissues, and MAP4, YWHAG, CEP135, and CEP250 differed significantly at the transcriptional level." (PMID 36705386, 2023). "Taken together, these data support our hypothesis that overexpression of YWHAG and the consequent excess of the 14-3-3γ protein contribute to the polyploidy frequently observed in human NSCLC and other carcinomas." (PMID 29321819, 2017). "We had analyzed the overexpression and poor prognostic value of YWHAZ, BRCA1, and YWHAG in BRCA, so can we reasonably speculate on developing a drug to inhibit YWHAZ, BRCA1, and YWHAG-related functions to suppress cancer progression and make patients have a good prognosis." (PMID 36673982, 2023). "In addition, YWHAG expression and autophagy are correlated with cancer progression in a stage‐dependent manner regardless of cancer type and model." (PMID 37759388, 2023). "The rest four genes (YWHAG, ATXN1, UBQLN4, and SMAD9) also ranked high because of its high degree in transition probability W. Although they are not presented in CGC, some evidences show that these four candidate genes have functional roles in cancer or cancer-related biological processes." (PMID 31888623, 2019). "Wild‐type cancer cells during EMT did not undergo apoptosis despite the elevated intracellular ROS, unlike their YWHAG‐knockdown counterparts, suggesting a cytoprotective mechanism embedded in the EMT‐associated network." (PMID 37759388, 2023).
tumor (22 papers, 2010 to 2024). "Finally, YWHAG deficiency leads to increased intracellular oxidative stress and impairs autophagy, substantially inhibiting tumor growth and metastasis." (PMID 37759388, 2023). "YWHAG expression perturbations align with intricate molecular interactions dictating tumour behaviour and therapy response." (PMID 37882107, 2024). "YWHAG, an oncogenic signaling adaptor protein, is a highly promising target against tumor metastasis." (PMID 37759388, 2023). "Together, these observations suggest that YWHAG contributes to the growth and metastatic potential of the primary tumor and reduces the overall median survival time." (PMID 37759388, 2023). "Silencing YWHAG diminishes primary tumor volumes, prevents metastasis, and prolongs the median survival period of the mice." (PMID 37759388, 2023). "Thus, network perturbations through the disruption of the regulome of YWHAG offer a potentially novel and effective strategy to curtail tumor metastasis." (PMID 37759388, 2023). "Disruption of the YWHAG regulome offers a new strategy to curtail tumor metastasis." (PMID 37759388, 2023). "Mutational and transcriptomic level studies revealed significant differences in DNA methylation, single nucleotide polymorphism, and transcript levels between YWHAG and MAP4 in normal tissues compared to tumor tissues, and differential expression of the 2 proteins in immunohistochemistry." (PMID 36705386, 2023). "YTN3shYWHAG allografted mice were fed a doxycycline diet only from the second week onward to suppress the expression of YWHAG, as premature inhibition of YWHAG resulted in the absence of the allografted tumor." (PMID 37759388, 2023). "Deliberate disruption of YWHAG regulome abolishes EMT, limiting secondary tumor growth effectively." (PMID 37759388, 2023).
infection (5 papers, 2011 to 2025). The state of being infected such as from the introduction of a foreign agent such as serum, vaccine, antigenic substance or organism. "In particular, DRE sites in Calmodulin 1 (Calm1: chr12: 100207186) and Tyrosine 3-Monooxygenase/Tryptophan 5-Monooxygenase Activation Protein Gamma (Ywhag: chr5: 135909342) were shared by 12 infection datasets, which were also predicted to exert a cis-regulatory effect on the gene expression." (PMID 37081881, 2023). "Next, we infected YWHAG-KO or control cells with PR8 virus at MOI = 0.01, the supernatants were collected at 12, 24, and 36 h post-infection (p.i.)and titrated on MDCK cells." (PMID 35928168, 2022).
psychiatric disorder (5 papers, 2020 to 2025). A disorder characterized by behavioral and/or psychological abnormalities, often accompanied by physical symptoms. "In particular, ESR1 has been implicated in psychiatric disorders, and YWHAG is known to modulate multiple signaling pathways relevant to mood regulation." (PMID 41325417, 2025). "Although the possible mechanisms involving 14-3-3 proteins in psychiatric disorders pathophysiology remain unknown, early overexpression of YWHAE and YWHAG has been shown to impair neurodevelopment, such as neuronal migration and neurite formation in animal models." (PMID 32555255, 2020).
neurological disorders (4 papers, 2016 to 2025). "While the YWHAG mutations responsible for neurological disorders are predominantly considered germline events, further research is required to distinguish between germline and somatic mutations in this context." (PMID 40896335, 2025).
YWHAG also shares sentences with these, for which no sentence is quoted: hepatocellular carcinoma (5 papers); Cognitive impairment (3); ischemia (3); osteosarcoma (3); Cerebral ischemia (2); colorectal cancer (2); dementia (2); diabetic nephropathy (2); early-onset epilepsy (2); leiomyoma (2); lymph node metastasis (2); neurodegenerative disease (2); Parkinson (2); prion disease (2); Seizure (2); Sepsis (2); Uterine leiomyoma (2); viral infection (2); Williams Beuren syndrome (2); autism spectrum disorder (1); behavioural disorders (1); brain diseases (1); breast adenocarcinoma (1); COVID-19 (1); diabetes (1); Down syndrome (1); genetic generalized epilepsy (1); Gliosis (1); head and neck cancer (1); hypercortisolism (1).
A further 21 diseases each share a sentence with YWHAG in 1 paper.